INO80 (INO80 complex ATPase subunit)
Description:
ATPase component of the chromatin remodeling INO80 complex which is involved in transcriptional regulation, DNA replication and DNA repair. Binds DNA. As part of the INO80 complex, remodels chromatin by shifting nucleosomes. Regulates transcription upon recruitment by YY1 to YY1-activated genes, where it acts as an essential coactivator. Involved in UV-damage excision DNA repair. The contribution to DNA double-strand break repair appears to be largely indirect through transcriptional regulation. Involved in DNA replication. Required for microtubule assembly during mitosis thereby regulating chromosome segregation cycle.
Synonyms: hINO80; INO80A; INOC1; KIAA1259
Tractability: Small molecule: a structure with a bound ligand is known. PROTAC: ubiquitination databases record sites on it; its protein half-life has been measured.
Target class: Enzyme; Hydrolase
Gene: Protein-coding gene on chromosome 15 (40,978,880 to 41,116,568, reverse strand). Ensembl gene ENSG00000128908.
Subcellular location: Cytoplasm; Nucleus; Cytoplasm, cytoskeleton, spindle; Chromosome
Subcellular location (Human Protein Atlas): Nuclear bodies; Nucleoplasm; Cytosol
Pathways (Reactome):
DNA Repair: DNA Damage Recognition in GG-NER
Metabolism of proteins: UCH proteinases
Gene Ontology:
Molecular function: alpha-tubulin binding; ATP hydrolysis activity; ATP-dependent activity, acting on DNA; DNA binding; protein binding; ATP binding; ATP-dependent chromatin remodeler activity
Biological process: cellular response to ionizing radiation; cellular response to UV; chromatin remodeling; double-strand break repair; double-strand break repair via homologous recombination; mitotic sister chromatid segregation; positive regulation of cell growth; positive regulation of DNA-templated transcription; positive regulation of nuclear cell cycle DNA replication; positive regulation of transcription by RNA polymerase II; regulation of cell cycle; regulation of chromosome organization; regulation of DNA replication; regulation of DNA strand elongation; regulation of G1/S transition of mitotic cell cycle; spindle assembly; UV-damage excision repair; DNA repair; chromosome organization; DNA metabolic process; DNA-templated transcription; positive regulation of DNA metabolic process; positive regulation of DNA repair; positive regulation of telomere maintenance in response to DNA damage; regulation of DNA repair; and 2 more
Cellular component: chromosome; cytoplasm; cytosol; Ino80 complex; nuclear body; nucleoplasm; nucleus; spindle
Genetic constraint (gnomAD): Loss-of-function variants: 15 observed, 140.08 expected, observed/expected ratio (o/e) 0.11, 90% interval 0.071 to 0.17. The upper end of that interval is the gene's LOEUF score, 0.17, which puts it in group 1 of 6, group 1 being the genes least tolerant of losing a copy. Missense variants: 1,202 observed, 1,617.4 expected, observed/expected ratio (o/e) 0.74, 90% interval 0.71 to 0.78. Synonymous variants: 613 observed, 599.77 expected, observed/expected ratio (o/e) 1.02, 90% interval 0.96 to 1.09.
Gene-disease validity (ClinGen):
ClinGen rates the evidence that INO80 causes each of these diseases.
immunodeficiency, common variable, 1 (autosomal recessive): Disputed.
Homologues: Orthologues: chimpanzee INO80 (99% identical), macaque INO80 (99% identical), dog INO80 (99% identical), pig INO80 (98% identical), rabbit INO80 (98% identical), guinea pig INO80 (98% identical), rat Ino80 (97% identical), mouse Ino80 (97% identical), tropical clawed frog ino80 (80% identical), zebrafish ino80 (75% identical), Drosophila melanogaster Ino80 (46% identical). Paralogues in human: SRCAP (23% identical), EP400 (21% identical), CHD2 (21% identical), CHD1 (20% identical), SMARCA1 (20% identical), SMARCA5 (19% identical), SMARCA4 (19% identical), CHD7 (18% identical), SMARCA2 (18% identical), HELLS (18% identical), CHD9 (18% identical), CHD3 (18% identical), and 18 more.
Diseases named in the same sentence as INO80 in open-access papers:
INO80 is named in the same sentence as 42 diseases in open-access papers, as found by Europe PMC text mining. Sharing a sentence is not in itself a finding about the gene and the disease. The quoted sentences say what the papers report.
melanoma (8 papers, 2017 to 2025). A malignant, usually aggressive tumor composed of atypical, neoplastic melanocytes. "Although several INO80 subunits are overexpressed in melanoma, cervical, and non-small cell lung cancer, according to TCGA data analysis the only INO80 gene significantly amplified in OC patients is ACT6LA, shared with SWI/SNF family remodelers." (PMID 36430148, 2022). "Depletion of INO80 in the NRAS mutant WM1361 melanoma cell line compromised cellular growth, while RNAse H1 overexpression in the siINO80 WM1361 cells rescued growth by approximately three-fold." (PMID 32913330, 2020). "For example, INO80 was recently shown to reduce nucleosome occupancy and promote oncogenic transcription in melanoma." (PMID 30240750, 2018). "In support of this possibility, a recent study showed that INO80 promotes tumor growth in melanoma, non-small cell lung cancer and cervical cancer by activating the transcription of cancer-associated oncogenes." (PMID 29383140, 2017). "Signature 3 in TWT melanoma tumors is associated with downregulation of ATM and methylation of INO80; however, the source of ATM downregulation is unknown." (PMID 38758740, 2024). "Through this, INO80 silencing selectively inhibits melanoma cell proliferation, tumorigenesis, and tumor maintenance in mouse xenografts, indicating that miR-372-INO80 complex regulatory axis may function as a tumor suppressor in cells." (PMID 37445863, 2023). "INO80 has been reported to promote growth of NRAS oncogene mutant-driven melanoma cells." (PMID 32913330, 2020). "While there is no information about the functions of the INO80 complex in neuroblastoma, a previous study has shown that INO80 occupies >90% of super-enhancers in melanoma, and its occupancy is dependent on transcription factors such as MITF95." (PMID 40962798, 2025).
cervical cancer (6 papers, 2016 to 2023). A primary or metastatic malignant neoplasm involving the cervix. "INO80 has also been found to be overexpressed in cervical cancer and has shown the ability to promote carcinogenesis through binding and activating the Nanog transcription start site (TSS) and improving the development of cervical cancer cells." (PMID 35327559, 2022). "In a mouse model of cervical cancer, INO80 was overexpressed and, when bound to the Nanog transcription start site, this transcription factor’s expression was enhanced." (PMID 33121134, 2020). "Collectively, these results demonstrate that Ino80 knockdown mainly induces G0/G1 phase cell cycle arrest in cervical cancer cells." (PMID 27750218, 2016). "Our data demonstrated that Ino80 bound Nanog transcription start site and activated its expression in cervical cancer cells." (PMID 27750218, 2016). "Our data demonstrated that Ino80 promoted cervical cancer cell proliferation in vitro and tumor growth in vivo." (PMID 27750218, 2016). "We also showed that Nanog overexpression in Ino80 knockdown cervical cancer cells promoted cell proliferation." (PMID 27750218, 2016). "To assess Ino80 expression in cervical cancer, we examined gene expression data from one published study consisting of 9 cervical cancer cell lines, 24 normal cervical tissues and 28 cervical cancer samples." (PMID 27750218, 2016). "Our observations are consistent with these reports, and confirm a role for Ino80 in cervical cancer cell proliferation." (PMID 27750218, 2016). "In this study, we demonstrated for the first time that Ino80 was upregulated in cervical cancer and promoted tumorigenesis." (PMID 27750218, 2016). "Ino80 knockdown inhibited cervical cancer cell proliferation, induced G0/G1 phase cell cycle arrest in vitro and suppressed tumor growth in vivo." (PMID 27750218, 2016). "In this study, we investigated the role of Ino80 in cervical cancer tumorigenesis, along with the related genetic and epigenetic regulatory mechanisms." (PMID 27750218, 2016). "Ino80 overexpression promoted proliferation in the H8 immortalized cervical epithelial cell line, which has low endogenous Ino80 expression as compared to cervical cancer cell lines." (PMID 27750218, 2016). "This study demonstrated for the first time that Ino80 was upregulated in cervical cancer and promoted cell proliferation and tumorigenesis." (PMID 27750218, 2016). "We hypothesized that Ino80 may promote cervical cancer tumorigenesis through elevating expression of these pluripotency factors." (PMID 27750218, 2016). "Ino80 expression was higher in cervical cancers as compared to corresponding pericarcinous tissues." (PMID 27750218, 2016). "We found that Ino80 was highly expressed in cervical cancer cell lines and tumor samples." (PMID 27750218, 2016). "Similarly, Ino80 expression was elevated in the human cervical cancer cell lines, HeLa, SiHa, C-33A, CaSki and MS751, compared to the immortalized cervical epithelial cell line, H8." (PMID 27750218, 2016). "Our findings suggest that Ino80 may be a potential therapeutic target for the treatment of cervical cancer." (PMID 27750218, 2016). "Our data suggests that Nanog may mediate the pro-proliferative effects of Ino80 in cervical cancer cell." (PMID 27750218, 2016). "Compared to normal cervical tissues, Ino80 was markedly upregulated in cervical cancer samples." (PMID 27750218, 2016). "We used flow cytometry to determine whether Ino80 was involved in cervical cancer cell cycle regulation." (PMID 27750218, 2016). "Our findings suggest that Ino80 may be a potential therapeutic target for cervical cancer." (PMID 27750218, 2016). "We hypothesized that Ino80 may also promote cervical cancer cell proliferation." (PMID 27750218, 2016). "However, H8 cells express lower levels of endogenous Ino80 than do cervical cancer lines." (PMID 27750218, 2016). "Therefore, we examined whether Ino80 knockdown affected cervical cancer cell apoptosis." (PMID 27750218, 2016).
cervical cancer (continued). "Collectively, these findings indicate that Ino80 binds to the Nanog TSS and enhances its expression in cervical cancer cells to promote tumorigenesis." (PMID 27750218, 2016). "Ino80 bound to the Nanog transcription start site (TSS) and enhanced its expression in cervical cancer cells." (PMID 27750218, 2016). "Another study demonstrated that the overexpression of INO80 and NANOG could promote cervical cancer cell proliferation and tumorigenesis." (PMID 38020889, 2023). "Studies using HeLa human cervical cancer cells and PC3 human prostate cancer cells have shown that INO80 performs a role in replication fork progression during normal DNA synthesis and in the process of recovering from replication stress induced by treatment with hydroxyurea." (PMID 29383140, 2017).
breast carcinoma (4 papers, 2020 to 2025). "Our analysis primarily focused on the effect of INO80 mutation on breast cancer subtype and changes in gene cohorts associated with breast cancer." (PMID 38020889, 2023). "INO80 copy number status is associated with breast cancer subtype, whereas patients with primary breast cancer and TNBC subtypes harbored higher odd ratios than did those with luminal or HER2 subtypes." (PMID 38020889, 2023). "Our analysis revealed that INO80 repression is associated with differential responsiveness of estrogen receptors (ERs) depending upon breast cancer subtype, ER networks, and increased risk of breast carcinogenesis." (PMID 38020889, 2023). "The odds ratio (OR) suggests that the risk of breast cancer is 6.5724 times higher in patients with INO80 deletion in the TNBC cluster than in those with other mutations, which is statistically significant [CI (4.55–9.49) and p < 0.0001]." (PMID 38020889, 2023). "While the association between INO80 and breast cancer has been demonstrated elsewhere, the specific function of the INO80 subunit and the underlying molecular mechanism involved in mammary development and breast cancer have not been fully elucidated." (PMID 38020889, 2023). "However, lower expression of INO80 is associated with reduced overall survival rate, distant metastasis-free survival, and recurrence-free survival in breast cancer patients." (PMID 41278204, 2025). "Therefore, our study suggests that the aberrant function of INO80 is potentially associated with breast cancer by modulating gene expression." (PMID 38020889, 2023). "In addition, unsupervised clustering from the WGCNA analysis revealed an association between patients with INO80 mutation and breast cancer biomarkers (ER/PR/HER2 IHC data)." (PMID 38020889, 2023). "Moreover, our analysis suggests that there is an increasing risk of breast cancer and reduced survival rates in patients harboring the INO80 mutation." (PMID 38020889, 2023). "Therefore, the findings suggest an underlying mechanism by which INO80 function is involved in mammary gland development and breast cancer." (PMID 38020889, 2023). "Therefore, our findings suggest that INO80 loss alone is insufficient to induce mammary tumor formation in mice." (PMID 38020889, 2023). "Non functional studies:INO80 expression is significantly downregulated in basal-type breast cancerReduced expression of INO80 is associated with reduced overall survival rate, distant metastasis-free survival, and recurrence-free survival in breast cancer patients." (PMID 41278204, 2025). "However, based on our breast cancer data analysis and the observed mammary gland phenotype, it is reasonable to hypothesize that INO80 may play a role in enhancing signaling abnormalities associated with breast cancer oncogenesis." (PMID 38020889, 2023). "In the TCGA breast cancer atlas cohort, the subunits of the INO80 complex are frequently amplified, accounting for alterations present in around 5% of overall breast cancer cases." (PMID 41278204, 2025). "Next, we aimed to determine the expression levels of INO80 in normal tissue and different breast cancer PAM50 subtypes, including basal, luminal A, luminal B, HER2, and normal-like." (PMID 38020889, 2023). "In breast cancer, INO80 expression is generally lower, although it correlates with the ER-positive breast cancer subtype." (PMID 38020889, 2023). "The Kaplan-Meier survival analysis of the TCGA dataset revealed that breast cancer patients with lower INO80 expression had reduced survival probabilities over a 150-month follow-up period." (PMID 38020889, 2023). "To investigate the contribution of the INO80 complex to breast cancer, we first examined the frequency of alteration in the expression of INO80 complex subunits in various cancer types using the cBioportal platform." (PMID 38020889, 2023).
breast carcinoma (continued). "In this study, we aimed to explore the functional role of INO80 in both breast cancer progression and mammary gland development through analysis of publicly available TCGA datasets and a conditional knockout (cKO) mouse model." (PMID 38020889, 2023). "Nevertheless, further investigation is required to determine the exact nature of INO80’s involvement in breast cancer development and progression." (PMID 38020889, 2023). "Meanwhile, a relatively higher level of mean INO80 expression was found in patients with luminal breast cancer classified as ER and/or progesterone receptor (PR) IHC-positive." (PMID 38020889, 2023). "Our findings demonstrate a significant, albeit heterogeneous, correlation between INO80 expression and breast cancer progression." (PMID 38020889, 2023). "In the present study, we have performed a weighted gene co-expression network analysis (WCGNA) to investigate links between INO80 expression and breast cancer sub-classification and progression." (PMID 38020889, 2023). "A remarkably lower expression of INO80 was found in all breast cancer subtypes, with significantly downregulated INO80 in the basal type compared with that in the normal sample." (PMID 38020889, 2023). "Previous studies have demonstrated the involvement of INO80 in stem cell differentiation and mammary tumors via the Wnt pathway and its regulation of BMP signaling in embryonic and liver cancer stem cells." (PMID 38020889, 2023). "Interestingly, INO80 showed an alteration frequency of 1%–8% in most cancer types and approximately 5% in all patients with breast cancer." (PMID 38020889, 2023). "Additionally, the analysis of the METABRIC dataset showed consistency with our TCGA data analysis, demonstrating a significant correlation between INO80 CNV and luminal signatures, as well as an association with the TNBC cluster compared to other breast cancer subtypes." (PMID 38020889, 2023). "Additionally, our study provides evidence to suggest that INO80 loss alone is not sufficient to induce the development of breast cancer in mice." (PMID 38020889, 2023). "Furthermore, the results from our WGCNA analysis indicated the existence of unknown networks between INO80 and a subset of luminal breast cancer biomarkers, including FOXA1, ESR1, GATA3, TFF1, and AR." (PMID 38020889, 2023). "On the other hand, lower expression of INO80 affects overall survival (OS) rate, Distant Metastasis-free survival (DMFS), and Recurrence-free survival (RFS) endpoints in breast cancer." (PMID 38020889, 2023).